CLDN1 (claudin 1)
Diseases named in the same sentence as CLDN1 in open-access papers (continued):
Sharing a sentence is not in itself a finding about the gene and the disease.
vasculopathy (1 paper, 2022). "A hallmark of CAA vasculopathy is BBB hyperpermeability with altered expression of major TJ proteins, claudin-5, ZO-1, claudin-1, and occludin." (PMID 35813502, 2022).
CLDN1 also shares sentences with these, for which no sentence is quoted: neurofibroma (5 papers); ischemia (3); colorectal adenoma (2); COVID-19 (2); deafness (2); dysplasia (2); focal segmental glomerulosclerosis (2); gastritis (2); gastrointestinal disease (2); gastrointestinal stromal tumor (2); hyperplastic polyp (2); mesothelioma (2); papillary thyroid carcinoma (2); peripheral nerve injury (2); portal hypertension (2); renal carcinoma (2); salmonellosis (2); tongue cancer (2); urothelial carcinoma (2); abscesses (1); acromegaly (1); alcoholic liver diseases (1); allergic asthma (1); Allergy (1); Alzheimer disease (1); anaplastic astrocytoma (1); anaplastic cancer (1); ANCA associated vasculitis (1); apocrine breast carcinoma (1); Ascites (1).
A further 92 diseases each share a sentence with CLDN1 in 1 paper.